IL6 (interleukin 6)
Diseases named in the same sentence as IL6 in open-access papers (continued):
Sharing a sentence is not in itself a finding about the gene and the disease.
Stroke (continued). "Together, this suggests that, although bethanechol reduced plasma VTN, which is expected to be beneficial after stroke in females, its side effects included increased detrimental IL‐6 expression in the injured striatum." (PMID 35531929, 2022). "From the heatmap, we observed that traits in high genetic correlations tend to have similar or dependent estimated causal effects of IL-6, e.g., COVID19 severity and susceptibility; any stroke (AS), any ischemic stroke (AIS), and cardioembolic stroke (CES)." (PMID 36310177, 2022). "In animal models of acute stroke, GLP-1RA reduce TNF and IL-6 levels, both pro-inflammatory cytokines involved in stroke pathology." (PMID 36636739, 2022). "Though the association between inflammatory indices and cognitive decline in post-stroke situations remains obscure, recent data suggest an involvement of IL-6 in PSCI." (PMID 36547090, 2022). "Studies investigating stroke demonstrate that IL-6 has neuroprotective effects via the regulation of oxidative stress and angiogenesis." (PMID 35625063, 2022). "Their activation and recruitment at the site of infarction always coincide with the maximum synthesis of proinflammatory mediators (such as TNF-α and IL-6) and associated biomarkers (such as CRP), which result in neuronal damage after stroke." (PMID 35978885, 2022). "It was also shown that a higher IL-6 concentration in the acute phase of stroke and assessed on day 1 and day 7 only at discharge was associated with poorer initial and late prognosis in patients treated with intravenous thrombolysis." (PMID 36142524, 2022). "In parallel to the decrease in neuroinflammation mediated by A. borbonica polyphenols and caffeic acid in obese mice during stroke, the quantities of IL-6 and TNF-α were also lowered by polyphenols in the visceral adipose tissue of obese mice." (PMID 35624723, 2022). "C-reactive protein (CRP), interleukin-6 (IL-6), and lipoprotein-associated phospholipase A2 (Lp-PLA2) are some of the inflammatory markers associated with stroke." (PMID 35872918, 2022). "In accordance with the present results, previous studies revealed that increased concentration of inflammatory biomarkers, including CRP, IL‐6, and TNF‐α, is associated with increased risks of the occurrence and worse prognosis of stroke." (PMID 35588444, 2022). "Initial levels of IL-6 have been shown to correlate with the severity of stroke (size of the lesion), perfusion-weighted imaging (PWI) signal, and the patient’s neurological score." (PMID 36142524, 2022). "By analysing inflammatory biomarkers between different types of strokes, we found statistically lower levels of IL-6 in patients with LACI-type AIS compared to PACI at <4.5 h." (PMID 36142524, 2022). "It has been reported that compared to controls, IS patients have higher IL-6, IL-8, and TNFα protein in plasma and lower IL-6, IL-8, TNFα, IL-1α, and IL-1β mRNA in leukocytes within 72 h after stroke." (PMID 36547090, 2022). "In the patients with ischemic stroke or TIA, IL-6 and YKL-40 were independently associated with recurrent stroke and poor functional outcome, and improved risk classification of clinical risk algorithms." (PMID 35761288, 2022). "Several pro‐inflammatory mediators such as TNF‐α, IL‐1β, and IL‐6 have been proposed as key drivers of secondary vascular events after stroke." (PMID 35971650, 2022). "In the multivariate stepwise regression analysis with backward selection, the associations between IL-6 (OR 1.34; 95% CI 1.19–1.52; P < 0.0001) or YKL-40 (OR 1.01; 95% CI 1.01–1.03; P = 0.004) and recurrent stroke remained significant." (PMID 35761288, 2022). "ELISA of plasma revealed significantly higher levels of IL-1β (P = 0.001) and IL-6 (P = 0.001) at baseline in stroke patients who later died." (PMID 35726919, 2022). "Neutrophils are the main source of IL-6 production in vitro and a primary source of IL-6 in stroke models in rats." (PMID 36033552, 2022).
Stroke (continued). "IL‐6 released after stroke can aggravate cerebrovascular damage by activating NMDI‐Rs and up‐regulating the enhancement of ET‐1 and JNK." (PMID 34792838, 2022). "Acute phase proteins, such as CRP, are produced in the liver in response to pro-inflammatory cytokines such as IL-6 and are also increased in the acute phase of stroke." (PMID 38566903, 2022). "The plasma level of IL-6, but not TNFα, sIL-6R, or IL-1ra, was higher in patients who developed depressive symptoms at 3 months after IS; plasma IL-6 predicted the severity of depressive symptoms at 3 months after stroke." (PMID 36547090, 2022). "Various cytokines such as tumor necrosis factor (TNF), IL-1, and IL-6 are known to regulate the tissue damage in stroke models, and therefore, play a crucial role in poststroke therapies." (PMID 36120593, 2022). "Blood IL‐6 levels increase after stroke in humans and mice, and systemic injection of IL‐6 can rapidly induce liver VTN expression in naïve rats." (PMID 35531929, 2022). "After review of these studies, it is apparent that IL-6 has differing roles in modulating neuroinflammation following stroke." (PMID 36555094, 2022). "IL-6 is one of the most studied biomarkers in stroke, as higher blood IL-6 concentration has been shown to positively correlate with severity and worse outcome and the incidence of post-stroke infection." (PMID 38566903, 2022). "Some animal stroke experiments have suggested that increased lymphocytes up-regulate the levels of IL-10 and inhibit the inflammatory cytokines such as IL-6 and TNF-α, thus playing a neuroprotective role." (PMID 35370926, 2022). "This heterogeneity in signaling makes IL-6 a complicated target for therapeutics because it has both toxic inflammatory and restorative roles in stroke pathophysiology." (PMID 36555094, 2022). "We found that the secreted levels of IL-6 were increased in stroke patient derived Mφ-MSC co-cultures, far more than healthy control derived Mφ-MSC co-cultures." (PMID 36277912, 2022). "The cytokines TNF-α and IL-6 modulated infarct evolution in the experimental stroke and therefore received much attention as putative markers of stroke severity and neurological outcomes in humans." (PMID 36142524, 2022). "As such, the prospect of STVNA as a treatment strategy to lower IL-6 levels in the advent of stroke is supported." (PMID 36145501, 2022). "Cytokines associated with inflammation in stroke, such as IL-1, TNF-α, IL-6, TGF-β and IL-10, are released and serve as intercellular messengers." (PMID 35795571, 2022). "Strikingly, the transcription levels of multiple pro-inflammatory factors including TNF-α, IL-1β and IL-6 were significantly down-regulated and the anti-inflammatory factor IL-10 was significantly up-regulated in the stroke lesions of kaempferol-treated rats." (PMID 36293548, 2022). "In another study, Ebselen was shown to be effective against focal ischemic injury induced by photothrombosis (a form of ischemic damage to the brain that results in a stroke) in rats by decreasing IL-6." (PMID 35563199, 2022). "The findings identified that IL-2, IL-6, IL-10, and IFN-γ were risk factors for stroke risk in AF patients (P < 0.05)." (PMID 35600045, 2022). "The increase in the pleiotropic cytokine, interleukin-6 (IL-6), which induces an acute inflammatory response, was also reported to be related with cognitive decline in patients with stroke." (PMID 35629013, 2022). "Interleukin-1β (IL-1β), tumor necrosis factor-α (TNF-α) and IL-6, are the main inflammatory factors that trigger and exacerbate the inflammatory response after stroke." (PMID 35281064, 2022). "Systemic elevations of IL-6 and TNF-α have been reported to be associated with cognitive decline and stroke recurrence." (PMID 35467483, 2022).
Stroke (continued). "A positive correlation was found between the concentration of IL-6 and TNF-α in patients with AIS during <4.5 h and on one day after the onset of stroke, which means that the concentration of IL-6 increases with the increase in TNF-α concentration." (PMID 36142524, 2022). "Lactobacillus ruminis induces the secretion of proinflammatory cytokine IL-8 by gut epithelial cells and is also involved in the elevation of IL-6 in the serum of stroke patients." (PMID 33549142, 2021). "During the early hours after the onset of stroke, there are increments of various cytokines such as interleukin-1 beta (IL-1β), interleukin-1 receptor antagonist (IL-1ra), interleukin-6 (IL-6), IL-8, IL-10, and tumor necrosis factor alpha (TNF-α)." (PMID 34072449, 2021). "In a review, a series of biomarkers, including cytokines, the WBC count, CRP and interleukin 6 (IL-6), were shown to participate specifically in stroke progression." (PMID 34856939, 2021). "We have shown that the cytokine interleukin 6 (IL-6) is essential for post-ischemic angiogenesis and improves the outcome after stroke." (PMID 35155612, 2021). "In stroke patients, serum IL-6 levels are increased and positively correlated with clinical outcome." (PMID 34943061, 2021). "Kaplan–Meier curves of the PolyVD and IL-6 groups appeared distinctly early in the first year, indicating that patients with PolyVD and IL-6 ≥ 2.64 pg/ml had the highest incidence of recurrent stroke." (PMID 33927687, 2021). "Of particular note is the evaluation of TNF-α and IL-6, whose serum levels increase in the acute phase of stroke as well as correlate with its cerebrospinal fluid (CSF) levels and stroke focus size." (PMID 34433866, 2021). "Mixed model also revealed that IL-6 secretion was also decreased from stroke monocytes at 5000 and 50000 nM aspirin with all atorvastatin concentrations." (PMID 33959001, 2021). "Plasma IL-6 predicted the severity of depressive symptoms at 3 months after stroke (β = 0.42, P = 0.03)." (PMID 33903586, 2021). "When analyzing the different stroke subtypes, it appeared that embolic strokes had the highest IL-6 levels." (PMID 35008440, 2021). "Within a few hours after stroke onset, there is a rise in the concentration of IL-6, which correlates well with stroke severity and worse prognosis, although other researchers have found opposite results." (PMID 35008440, 2021). "The study has indicated that TNF-α, IL-1β, and IL-6 secreted by activated microglia involve in neuronal cell apoptosis at stroke onset." (PMID 34257822, 2021). "These mediators include proinflammatory cytokines such as interleukin 1 beta (IL-1β) and interleukin 6 (IL-6), which are released intracranially after a stroke and are responsible for local inflammation." (PMID 34393969, 2021). "Diverse stroke studies underscored the significant increase in the levels of IL-6 immediately after stroke onset." (PMID 34691061, 2021). "The role of inflammation in stroke recurrence, investigated by traditional biomarkers such as IL-6 and CRP, has been well established." (PMID 34879833, 2021). "Other candidate genes include Interleukin-6 (IL-6) and CDKN2A/CDKN2B which have been implicated as sources of the racial disparities in stroke incidence." (PMID 34828431, 2021). "The levels of inflammatory cytokines IL-1β, TNFα, and IL-6 in the blood of stroke patients and MCAO/R mice are increased." (PMID 34422821, 2021). "Combination of atorvastatin and aspirin had additive effect on reducing the secretion of IL-6 from co-cultures of stroke Mo and MSCs." (PMID 33959001, 2021). "In the present work, we further showed that treatment with QSYQ (600 mg/kg) significantly reduced the mRNA levels of TNF-α and IL-6 in brain tissues of stroke rats after ischemia and reperfusion." (PMID 33953667, 2021). "The predominant source of IL-6 in the CNS is reactive astrocytes, and while they retain IL-6 levels low in the normal brain, they elevate IL-6 expression during injury, stroke, inflammation, and infection." (PMID 33897376, 2021).
Stroke (continued). "We found increased levels of IL-6 post-stroke, pointing towards an activation of classical monocytes." (PMID 33918875, 2021). "The effect of daily melatonin administration in the acute phase of stroke on inflammation (i.e., IL-6 systemic levels) is currently under investigation in a randomized controlled trial (NCT03843008)." (PMID 33670976, 2021). "Background and purpose: Stroke is a dynamic process in terms of molecular mechanisms, with prominent glutamate-mediated excitotoxicity at the onset of symptoms followed by IL-6-mediated inflammation." (PMID 34300300, 2021). "Consistent with this, high IL-6 serum levels 6 and 72 h post-stroke correlated with poor outcome 3 months post-stroke." (PMID 34884906, 2021). "This supports the study of elevated pro-inflammatory IL-6 in the blood at 12 h after cerebral ischemia in stroke patients compared to controls, and this increase has been correlated with severe neurological deficits and worse outcomes." (PMID 33922467, 2021). "We found that IL-1β and IL-6 levels were increased solely 24-h after stroke in Wistar rats (F = 3.351 *p < 0.05; F = 4.455 *p < 0.05 respectively)." (PMID 34408211, 2021). "Combination of atorvastatin and Aspirin decreases the IL-6 secretion from stroke Mo-MSCs co-cultures after 24 h of exposure." (PMID 33959001, 2021). "The clear difference observed in serum levels of glutamate and IL-6 with the passing of time in the different quartiles suggests that they can be used as biomarkers to establish a time range in which stroke symptoms began." (PMID 34300300, 2021). "It has been established that both PSD and stroke involve an increase in pro-inflammatory cytokines, in particular IL-1β, IL-6, IFN-γ and TNF-α." (PMID 33919670, 2021). "IL-6 is low expressed in normal brain tissue but significantly elevated in response to injury, infection, stroke, and inflammation." (PMID 34504432, 2021). "The enhanced serum levels of TNF and IL-6 in stroke patients were tested on days 1, 3, and 7 after stroke when compared to the control group." (PMID 33953667, 2021). "Elevated levels of IL-1β and IL-6 after cerebral ischemia are correlated with the stroke volume, severity and long-term outcome." (PMID 34408211, 2021). "PSD is the most common clinical complication and sequelae of stroke, studies have shown that the levels of IL-6, IL-1β, and Hcy in patients with PSD are significantly higher than those in the normal population." (PMID 34040550, 2021). "Meanwhile, VPA reduced dMCAo-induced elevation of IL-6 at 24 h post-stroke and significantly decreased the number of CD11b-positive microglia within peri-infarct cortex at 7 days." (PMID 34122007, 2021). "On contrast testing, it was found that systemic (p=0.061) and intracranial (p=0.049) IL-6 were specifically higher in severe stroke (NIHSS = 15-24) compared to mild stroke (NIHSS < 5)." (PMID 35126360, 2021). "During the acute period after stroke, microglia secrete pro-inflammatory cytokines IL-6, TNF-α, and IL-1β, which can induce secondary cytotoxicity." (PMID 33479185, 2021). "Generally, elevated levels of circulating proinflammatory cytokines, including tumour necrosis factor-alpha (TNF-α), IL-6, and interleukin 1β (IL-1β), are related to a poor prognosis in stroke sufferers." (PMID 34335867, 2021). "Exhaled decanal levels steadily increased over the first 7 days after stroke onset, in parallel to blood CRP and IL-6 concentration, suggesting that decanal is likely associated with systemic inflammation." (PMID 34753981, 2021). "Salivary TNF-α, IL-6, and IL-10 as well as TNF-α/IL-10 and IL-6/IL-10 ratio significantly distinguish stroke patients from controls with high sensitivity and specificity." (PMID 34433866, 2021). "We tested the effects of MEDS-23 on levels of the inflammatory mediators IL-6 and TNF-α in brains of post-stroke rats to elucidate a possible association between its antipyretic effect and its correlation with neuro-inflammation." (PMID 35053779, 2021).
Stroke (continued). "Studies suggested that depressive symptoms are positively associated with inflammatory factors (i.e., C-reactive protein, IL-6, and Tumor necrosis factor alpha), which are related to stroke." (PMID 34706692, 2021). "A meta-analysis of 24 studies included 4,112 stroke patients with IL-6 levels in the 4th quartile that were independently associated with poor functional outcomes in the short-term follow-up." (PMID 33927687, 2021). "Other studies suggested that EE enhanced post-stroke angiogenesis via astrocytic HMGB1/IL-6 signaling pathway." (PMID 33841116, 2021). "As plasma IL-6 levels obtained within the first week post-stroke have been shown to correlate with brain infarct volume, stroke severity, and long-term outcome, we also investigated plasma IL-6 levels and their possible correlation with TNF, TNFR1, and TNFR2." (PMID 33918875, 2021). "Using R-7050 as an intervention agent, the changes in enhanced brain TNFRI, NF-κB signaling molecules, and IL-6 expression in stroke rats subsided, along with increased levels of the Nrf2 protein." (PMID 34073455, 2021). "M1 is activated through the classical pathway, expressing CD16 and iNOS on cell membranes, and secretes inflammatory factors such as tumor necrosis factor-α (TNF-α) and interleukin-6 (IL-6), which exacerbate post-stroke brain injury." (PMID 33790947, 2021). "Higher plasma concentrations of IL-6 on the first day of stroke impacts the neurologic and functional status of patients early in disease progression." (PMID 35126360, 2021). "These experimental studies are further corroborated by VaD and post-stroke patient studies, which both show increases in TNF-α, IL-1β and IL-6 within the CSF/serum that are associated with cognitive decline." (PMID 34884906, 2021). "IL-6 is a pro-inflammatory molecule and mediates stroke-induced inflammation and also increases MC maturation." (PMID 32429999, 2020). "In stroke mice, the hypothermia treatment markedly reduced the mRNA level of pro-inflammatory factors TNF-α and IL-6 at 1 to 3 days after stroke and IL-6 l at 1 and 7 days after stroke, respectively." (PMID 32010477, 2020). "As markers and mediators of systemic inflammation, increases in inflammatory cytokines, such as interleukin (IL)-2, IL-6, myeloperoxidase, and integrins, are abundant in polymorphonuclear neutrophils and are related to oxidative stress after a stroke." (PMID 32231119, 2020). "More importantly, captopril increased the secretions of IL-6 from cocultures of MSCs with stroke-Mo at therapeutically relevant doses at 24 hours (5000 nM to 50 nM, p < 0.05)." (PMID 32802081, 2020). "Relevant reduction of TNFα and IL-6 expression, microglia and vascular activation have been demonstrated by the authors in a mouse model of stroke." (PMID 32974295, 2020). "In a study that evaluated patients after acute ischemic stroke at days one and 8 PCS, it was reported that IL‐6 not only predicts both stroke and infarct severity and patient prognosis (Rodríguez‐Yáñez & Castillo, 2008)." (PMID 32583980, 2020). "Given the age-related increases in neutrophil-activating cytokines in mice after stroke, we next examined serum levels of IL-6 and IL-8 (the human homolog of murine CXCL1) in ischemic stroke patients and controls at 24 hours." (PMID 31927534, 2020). "On the other hand, in a rat model of cerebral ischemia, the damage due to stroke was meaningfully reduced after giving recombinant human IL-6." (PMID 32899616, 2020). "IL6 and infarction size were reported as independent predictors of short-term stroke outcome in young Egyptian adults." (PMID 31899762, 2020). "The only significant change was with captopril, which increased IL-6 secretion from cocultures involving stroke-Mo but reduced IL-6 from cocultures with healthy Mo." (PMID 32802081, 2020).